SCD5 (stearoyl-CoA desaturase 5)
Diseases named in the same sentence as SCD5 in open-access papers (continued):
Sharing a sentence is not in itself a finding about the gene and the disease.
melanoma (13 papers, 2018 to 2025). A malignant, usually aggressive tumor composed of atypical, neoplastic melanocytes. "In the present study we searched for the regulatory mechanisms and factors underlying SCD5 expression in differently staged melanoma cell lines." (PMID 29484133, 2018). "In view of SCD5 decrease associated with melanoma progression, we looked for the mechanisms possibly underlying its regulation." (PMID 29484133, 2018). "We then looked for different SCD5 mRNA and/or protein stabilities associated with melanoma progression." (PMID 29484133, 2018). "On this basis, we investigated the regulatory mechanisms underlying SCD5 down-regulation associated with melanoma progression." (PMID 29484133, 2018). "Looking for the regulatory mechanisms underlying SCD5 reduced expression during melanoma progression, we demonstrated a significantly lower stability of SCD5 protein as well as the direct targeting of SCD5 mRNA by the oncogenic miR-221&222 in metastatic cell lines." (PMID 29484133, 2018). "Inhibition of tumor cell differentiation by SCD5 expression has been documented in advanced melanoma." (PMID 41463832, 2025). "Enforced expression of SCD5 in melanoma cells inhibits the secretion of extracellular matrix proteins, with the consequent impairing of tumor spreading." (PMID 36980176, 2023). "Re-expression of SCD5 drove advanced melanoma cells toward differentiation, and reversed the epithelial-mesenchymal process." (PMID 36980176, 2023). "In advanced melanoma, where SCD5 is downregulated, its re-expression modified extracellular matrix proteins and reversed the epithelial-mesenchymal-like process." (PMID 36980176, 2023). "SCD5 mRNA is targeted by the oncogenic miR-221 and miR-222, and this correlates with melanoma progression." (PMID 36980176, 2023). "SCD5 downregulation is evident in advanced melanoma, and restoring its expression can suppress malignancy via decreasing protease and ECM-related protein secretion." (PMID 38090559, 2023). "Intriguingly, the SCD5 expression level is reduced in melanoma; while restoration of SCD5 suppresses the formation of malignant melanoma through a reversed EMT-like process and induction of cancer cell differentiation." (PMID 32641978, 2020). "On the other hand, SCD5 acts as a tumor suppressor in melanoma, with the cancer reducing its expression." (PMID 32392704, 2020). "SCD5 was highly expressed in primary tumors, where this couple of miRs was barely or not detectable, whereas the opposite pattern was visible in advanced melanomas." (PMID 29484133, 2018). "The expression pattern of SCD5 was then analyzed in Me1007 melanoma enforced to lentivirally express miR-221 or miR-222." (PMID 29484133, 2018). "More important, the enforced expression of SCD5 in the A375M metastatic melanoma cell line was able to significantly reduce its aggressiveness including the capability of these cells to produce metastases in an in vivo model of Nu/Nu mice." (PMID 29484133, 2018). "IHC, besides confirming the presence of human melanoma cells positive for SCD5, showed evident nests with a clear induction of E-cadherin correctly localized at cell membranes." (PMID 29484133, 2018). "In line with Denecker, which showed ZEB1 and ZEB2 inverse modulation and the presence of ZEB2 as a positive prognostic factor for melanoma patients, we observed the SCD5-dependent up-regulation of ZEB2 paralleled by reduced amounts of ZEB1." (PMID 29484133, 2018). "More important, IHC analysis, besides confirming the presence of human melanoma cells highly positive for SCD5, showed the induction of E-cadherin, but also its correct localization at cell membrane levels." (PMID 29484133, 2018). "Actually, SCD5 re-expression in advanced melanomas was able to favor a less-invasive, more differentiated phenotype associated with a partial remodulation of the EMT." (PMID 29484133, 2018).
melanoma (continued). "A similar miR-dependent repression of SCD5 was obtained when the luciferase assays were performed by transfecting the 3′UTR regions of SCD5, either wt or mutated, into the Me1007 melanoma cell line stably overexpressing miR-221 or miR-222." (PMID 29484133, 2018). "All together these changes indicate that SCD5 restored expression reduces the metastatic potential of melanoma cells by favoring a Mesenchymal-to-Epithelial transition." (PMID 29484133, 2018). "SCD5 is significantly expressed in primary melanoma, but becomes barely detectable at tumor advanced stages." (PMID 29484133, 2018). "During melanoma progression SCD5 expression was down-regulated, being highly expressed in primary compared to more advanced melanomas, where it is barely detectable." (PMID 29484133, 2018). "Essentially, we detected a significantly more stable SCD5 protein in primary compared to metastatic melanoma cell lines, in good agreement with the expression pattern detected in our panel of cell lines." (PMID 29484133, 2018). "Accordingly, in antagomiR-treated A375M metastatic melanoma cells, we observed the induction of SCD5 after miR-221 and/or -222 inhibitions." (PMID 29484133, 2018). "In addition, SCD5 was reported to be significantly higher in primary and low-invasive melanoma than in metastatic cell lines or in five independent cultures of normal melanocytes, at both the mRNA and protein levels." (PMID 37373069, 2023). "According to this hypothesis, SCD5 levels appeared compatible with miR-221&222 targeting evaluated by qRealTime PCR and western blot in melanoma cell lines as well as by in situ hybridization and immunohistochemistry on primary bioptic samples." (PMID 29484133, 2018). "The functional involvement of SCD5 in some circuitries of the oncogenic transformation was confirmed by the induction of key differentiation and antineoplastic genes consequent to its restored expression in advanced melanomas." (PMID 29484133, 2018). "Thus, we can consider SCD5 as an upstream factor able to directly or indirectly regulate proliferation and differentiation in melanoma." (PMID 29484133, 2018). "Indeed, at advanced melanoma stages, as a consequence of SCD5 restored expression we evidenced MITF up-regulation paralleled by miR-221&222 decreases." (PMID 29484133, 2018). "Thus, the up-regulation of SCD5 expression in human melanomas appear able to restore their sensitivity to ATRA treatment slowing down their cell growth and favoring differentiation." (PMID 29484133, 2018). "Indeed, qRealTime PCR confirmed a 40–50% reduction of miR-221&222 expressions in A375M and Me1402/R melanomas overexpressing SCD5." (PMID 29484133, 2018). "Indeed, a shorter protein half life of SCD5 was evidenced in advanced melanoma compared to primary ones, supporting the presence of biological processes aimed at preventing accumulation of SCD5 in metastatic cells." (PMID 29484133, 2018). "As SPARC is involved in the transition from epithelial to mesenchymal phenotypes, we have hypothesized the possible contribution of SCD5 in reversing the EMT-like process described in melanoma." (PMID 29484133, 2018). "In addition, microRNAs (miRs) have been shown to regulate SCD5 expression in melanoma cells." (PMID 36980176, 2023). "Studies in melanoma found that SCD5 could protect against metastatic progression." (PMID 36980176, 2023). "In addition we observed a significant SCD5-dependent down-regulation of Preferentially Expressed Antigen in Melanoma (PRAME), a melanoma antigen causally implicated in tumor transformation and acting as a dominant inhibitor of the retinoic acid receptor (RAR) pathway." (PMID 29484133, 2018). "Also, we showed how SCD5 re-expression and the direct supplementation of its main product oleic acid (OA) can drive advanced melanoma cell lines toward differentiation and reversion of the epithelial-mesenchymal (EMT)-like process, eventually inducing a less malignant phenotype." (PMID 29484133, 2018).
melanoma (continued). "Here we evaluated whether SCD5 might enhance melanoma sensitivity to ATRA treatment." (PMID 29484133, 2018). "Indeed SCD5 down-regulation appears functional to melanoma progression." (PMID 29484133, 2018). "Considering the reduced spreading of melanoma cells overexpressing SCD5 and the increased expression of MITF, we evaluated whether miR-221&222 levels were modulated by the presence of SCD5." (PMID 29484133, 2018). "As in melanoma the EMT-like process is influenced by the action of SPARC, we evaluated whether SCD5 restored expression might be able to modulate the transcription factors playing a key role in this program." (PMID 29484133, 2018). "All together these results demonstrate the lack of SCD5 as central to melanoma progression." (PMID 29484133, 2018). "Also, in view of our previous studies demonstrating the SCD5-dependent intracellular retention of SPARC and considering the known involvement of SPARC itself in supporting a mesenchymal-like phenotype, we looked for the possible SCD5 capability in reversing the EMT-like process in melanoma." (PMID 29484133, 2018).
Obesity (7 papers, 2016 to 2025). Accumulation of substantial excess body fat. "Although SCD5 appears to be a major regulator of visceral fat deposition and distribution in a zebrafish model system, its polymorphisms have not been investigated at all in the research on the genetic basis of obesity-related conditions." (PMID 36292669, 2022). "Although the role of SCD1 in the development of obesity-related conditions is a relatively clear and widely investigated topic, the potential relationship of SCD5 in diabetes is only now beginning to be noticed." (PMID 36292669, 2022). "Despite the numerous studies focusing on the role of SCD5 in the regulation of lipid metabolism, the importance of this gene product in the mechanism of human metabolic diseases such as diabetes and obesity has been poorly characterized." (PMID 36292669, 2022). "Expressing the human SCD5 in the livers of Scd1 GKO mice reversed several metabolic effects of Scd1 ablation, such as protection against obesity, hyperglycemia, and hepatic steatosis." (PMID 40350036, 2025).
autoimmune disease (5 papers, 2013 to 2023). A disorder resulting from loss of function or tissue destruction of an organ or multiple organs, arising from humoral or cellular immune responses of the individual to their own tissue constituents. "In fact, increased serum levels of sCD5 and sCD6 has been found in subjects diagnosed with RA but also other autoimmune diseases such as primary Sjögren’s syndrome, systemic inflammatory response syndrome, multiple sclerosis or dermatitis." (PMID 34777329, 2021). "Although the functional role of both soluble scavengers in autoimmune diseases is still under investigation, it is well established that sCD5 and sCD6 are regulators of T cell functions and induce autoreactivity." (PMID 34777329, 2021).
diabetes (5 papers, 2020 to 2026). "Its biological importance to the developing fetal lung is uncertain, although SNPs in the SCD5 promoter region have been linked to diabetes mellitus." (PMID 39901164, 2025). "In the present study, we identified the functional promoter region of the SCD5 gene and examined the functional impact of rs6841081 and rs3811792 SCD5 promoter polymorphisms and their potential association with diabetes." (PMID 36292669, 2022). "In conclusion, the minor allele of rs3811792 polymorphism might contribute to the development of diabetes by influencing the SCD5 promoter activity." (PMID 36292669, 2022). "Among these, NFATC2, which prefers the C allele of the rs3811792 polymorphic SCD5 promoter, was confirmed by several predictive programs, and this polymorphism was also shown to modify the promoter activity and to be associated with diabetes." (PMID 36292669, 2022). "It is proved that SCD5 may contribute to the development of T2DM, since SCD5 was identified as a master regulator of fat distribution, which plays a significant role in determining the visceral adipose tissue accumulation, which is a major risk factor for diabetes." (PMID 36292669, 2022). "In any case, it is certain that the two types of diabetes are complex multifactorial conditions that develop on the basis of several genetic and environmental factors, and so the rs3811792 SNP of the SCD5 promoter may only be one factor in this complex system." (PMID 36292669, 2022). "The present work is pioneering regarding not only the functional characterization of these factors, but also the association analysis of them, since no one has investigated the association of a single SCD5 polymorphism with diabetes before, although it would be plausible given the function of SCD1." (PMID 36292669, 2022).
neuroblastoma (4 papers, 2011 to 2021). Neuroblastoma (NB) is the most common solid, extracranial childhood tumor. "Of note, SCD5 is expressed ∼80% less than SCD1 in our neuroblastoma model but still influenced accumulation formation." (PMID 34301719, 2021). "This notion is supported by our findings that levels of SCD5 protein remained unchanged during the course of differentiation of SH-SY5Y human neuroblastoma cells with retinoic acid, and in similar incubations with retinoic acid in differentiated skin fibroblasts." (PMID 22745828, 2012). "To begin assessing the metabolic and biological implications of SCD5 expression, we established a cell model of SCD5 expression in mouse neuroblastoma Neuro2a cells, which do not naturally express SCD5." (PMID 22745828, 2012). "Incubation of SH-SY5Y human neuroblastoma cells with 10 μM RA for 96 h, a treatment that leads to induction of neuronal differentiation, also failed to change the levels of SCD5 protein in these cells." (PMID 22745828, 2012).
glioma (3 papers, 2020 to 2022). A benign or malignant brain and spinal cord tumor that arises from glial cells (astrocytes, oligodendrocytes, ependymal cells). "Nevertheless, in glioma, SCD5 tumors may not be significant in tumor development." (PMID 32392704, 2020).
Parkinson disease (3 papers, 2012 to 2023). A progressive degenerative disorder of the central nervous system characterized by loss of dopamine producing neurons in the substantia nigra and the presence of Lewy bodies in the substantia nigra and locus coeruleus. "Finally, given the mounting evidence suggesting a mechanistic association of abnormal Wnt signaling with Alzheimer's and Parkinson's diseases, our findings suggest that SCD5 may be a molecular link between signaling and lipogenic pathways mechanisms and these neurodegenerative conditions." (PMID 22745828, 2012).
Cognitive impairment (2 papers, 2024 to 2026). Abnormal cognition is characterized by deficits in thinking, reasoning, or remembering. "And the other two pairs of gene–gene interactions may be related to hippocampus, neuronal cells and cognitive impairment: TESPA1–OPCML and SCD5–SORBS1." (PMID 38368488, 2024).
dyslipidemia (2 papers, 2009 to 2025). "Dysregulation of SCD5 may play a role in dyslipidemia, characterized by abnormal lipid levels in the blood." (PMID 40585306, 2025). "Therefore, understanding the interplay between SCD5, dyslipidemia, and VEGF inhibition could yield valuable insights into CRC pathogenesis and therapeutic strategies." (PMID 40585306, 2025).
glioblastoma (2 papers, 2020 to 2023). The most malignant astrocytic tumor (WHO grade IV). "However, according to data from the GEPIA portal, the expression of SCD5 is elevated in glioblastoma tumors." (PMID 37046844, 2023). "The expression of SCD5 in glioblastoma tumors does not differ from that of nontumor brain tissue." (PMID 37046844, 2023).
squamous cell carcinoma (2 papers, 2018 to 2024). A carcinoma arising from squamous epithelial cells. "In fact, a pro-survival role was reported for SCD1 in lung cancer-initiating cells as well as in human lung carcinoma or squamous cell carcinoma of the hypopharynx, but not for SCD5, whose potential role in human disease remains largely unknown." (PMID 29849946, 2018).
type 2 diabetes (2 papers, 2013 to 2026). "Beyond cancer, genetic polymorphisms and expression alterations of SCD5 have been linked to neurodegenerative diseases, psychiatric conditions like schizophrenia, and metabolic dysfunctions such as visceral adiposity and type 2 diabetes." (PMID 42285304, 2026). "Previous studies had proposed that scd1 were associated with a variety of diseases including cancers, type 2 diabetes, and cardiovascular disorders, whereas scd5 might act a potential role for maintaining the optimum levels of oleic acid in brain development and physiological activities." (PMID 24312911, 2013).
anaplastic thyroid carcinoma (1 paper, 2020). "SCD5 expression is also increased in anaplastic thyroid carcinoma, which may indicate that SCD5 has important functions in that cancer." (PMID 32392704, 2020).
brain cancer (1 paper, 2012). A primary or metastatic malignant neoplasm affecting the brain. "Lastly, our studies suggest a value for SCD5 as a potential target for clinical interventions in poorly-treated neurological diseases such as brain cancer, Alzheimer and other neurodegenerative conditions." (PMID 22745828, 2012).
COVID-19 (1 paper, 2022). A disease caused by infection with severe acute respiratory syndrome coronavirus 2. "By comparing the upregulated genes between COVID-19 patients and recovered individuals, we found that 21 genes (i.e., RPL4, MT-ND2, SCD5, MT-CYB, EZR) were shared between the conditions." (PMID 36059456, 2022).
hearing loss (1 paper, 2025). "Both the variants identified in the patient within the REST and SCD5 genes have never been characterized or directly associated with hearing loss and are classified as VUS according to the ACMG guidelines." (PMID 40121402, 2025).
kidney cancer (1 paper, 2023). Primary or metastatic malignant neoplasm involving the kidney. "Analysis of the CPTAC mass-spectrometry-based proteomic tumor dataset showed that SCD5 protein levels were significantly lower in primary kidney cancer samples compared to control kidney samples." (PMID 36980176, 2023).
lipidosis (1 paper, 2022). "In addition, we first reported that ssc-miR-133a-3p, ssc-miR-486 and ssc-miR-1 regulate the target genes CPT1A, SCD5 and SCD, respectively, in the PPAR signaling pathway so that they can have an impact on lipidosis." (PMID 36672834, 2022).
metastatic melanoma (1 paper, 2018). A melanoma that has spread from its primary site to another anatomic site. "Indeed, SCD5 re-established the sensitivity to all-trans retinoic acid in A375M metastatic melanoma, associated with increased levels of Tyrosinase, melanin production and reduced proliferation." (PMID 29484133, 2018). "Our previous studies showed SCD5 significantly higher expression in primary than in metastatic melanoma cell lines where it was barely detectable." (PMID 29484133, 2018). "Indeed, SCD5 overexpression in metastatic melanoma was sufficient to reduce PRAME, in turn activating MITF and SOX9, which were further increased by ATRA." (PMID 29484133, 2018).
pancreatic cancer (1 paper, 2013). "However, most of the miRNAs predicted to target the 3′-UTR region of scd5 gene are related to the neurogenic disease and pancreatic cancer; and only 2 microRNAs are associated with the NAFLD." (PMID 24312911, 2013).
renal clear cell carcinoma (1 paper, 2025). "Previous studies have reported that SCD5 suppresses proliferation in renal clear cell carcinoma, demonstrating its conserved anti-proliferative function." (PMID 41463832, 2025).
T-cell acute lymphoblastic leukemia (1 paper, 2025). Acute lymphoblastic leukemia of T-cell origin. "Diminished expression of surface CD5 (sCD5) is associated with several pathological conditions, including systemic lupus erythematosus, multiple sclerosis, B-cell chronic lymphocytic leukemia, and T-cell acute lymphoblastic leukemia (T-ALL)." (PMID 40788503, 2025).